PML (PML nuclear body scaffold)
Diseases named in the same sentence as PML in open-access papers (continued):
Sharing a sentence is not in itself a finding about the gene and the disease.
tumor (continued). "Therefore, it was concluded that despite the presence of a functional gene, the PML protein is post-translationally degraded through proteasome-dependent mechanisms and its loss was generally associated with both tumor grade and progression." (PMID 23936764, 2013). "However, in murine experimental models of cancer, PML loss can cooperate with some oncogenic lesions to increase tumor initiation and progression." (PMID 23847764, 2013). "PML is a key factor in the formation of PML nuclear bodies (PML-NBs), which are distinct nuclear multi-protein complexes that have been associated with critical cellular processes, including tumor suppression, gene regulation, post-translational modifications, and protein catabolism." (PMID 23459691, 2013). "Consequently, a point mutated version of PML that is refractory to CK2 phosphorylation displays increased tumor-suppressive functions." (PMID 23293771, 2012). "Moreover, PML expression is lost in a number of solid tumors, the loss being correlated with tumor progression." (PMID 21998700, 2011). "PML protein levels when compared to normal cells were found to be low in cancers including cervical, breast, lung and colon among others, correlating PML deficiency with tumorigenesis, while loss of the Pml gene in a mouse model markedly accelerated tumour onset, incidence and progression." (PMID 34215258, 2021). "PML NBs have been functionally linked to apoptosis, nuclear proteolysis, senescence, stem cell renewal, regulation of gene expression, tumor suppression, the DNA damage response, telomere elongation and stability, epigenetic regulation, and antiviral responses." (PMID 29888200, 2018). "This may explain why the loss of PML from MAMs promoted tumor growth and increased chemoresistance by simultaneously increasing resistance to apoptotic stimuli and, through the stimulation of autophagy, adaptation to metabolic stress and anticancer therapy-mediated cellular damage." (PMID 28868254, 2017). "Then, loss of PML NBs during tumor progression could reflect loss of this senescence failsafe." (PMID 23847762, 2013). "The promyelocytic leukemia protein (PML) is a stress-response factor that assembles into PML nuclear bodies, dynamic subnuclear compartments involved in tumor suppression and antiviral defense." (PMID 41756868, 2026). "Turning to the stability and nuclear translocation of STAT1, PML, a recognized tumor suppressor protein, is reduced in advanced gastric cancers but further contributes to creating an immune-enhanced tumor microenvironment." (PMID 40909948, 2025). "Both mRNA expression and protein levels of PML were overexpressed based on the data of The Cancer Genome Atlas (TCGA) and National Cancer Institute’s Clinical Proteomic Tumor Analysis Consortium (CPTAC)." (PMID 40723250, 2025). "In the hypoxic tumor microenvironment, KLHL20 at elevated levels targets PML for constitutive degradation, reducing the number of PML-NBs and impairing tumor-suppressive functions." (PMID 40002221, 2025). "Accordingly, E6AP has been reported to affect several tumor-linked cellular pathways, including Pi3K/AKT-, Wnt/β-Catenin-, PML-, and HIPPO-signaling, which all also have been linked to senescence regulation." (PMID 39919145, 2025). "Regulation of the PML protein, a known tumor suppressor, largely depends on several phosphorylations of the protein." (PMID 40075679, 2025).
tumor (continued). "Research has indicated that promyelocytic leukemia protein (PML) influences cellular proliferation and tumor inhibition through the modulation of apoptotic signals, and deactivation of PLM completely abrogates the proapoptotic ability of Daxx." (PMID 40296918, 2025). "The stabilization of PML-NBs by p62 is of fundamental biological importance because PML-NBs play important roles in tumor suppression." (PMID 41247240, 2025). "Pathognomonic of APL, PML::RARα fusion protein rewires metabolic pathways to feed anabolic tumor cell’s growth." (PMID 40931045, 2025). "Conversely, lactylation upregulates ALKBH3 while disrupting tumor-suppressive promyelocytic leukemia protein (PML) nuclear bodies via m1A demethylation of SP100A, promoting cancer aggressiveness." (PMID 40860191, 2025). "Alongside the tumor-suppressive functions of PML, this coordinated activity preserves genomic integrity and ensures proper hematopoietic differentiation." (PMID 41440764, 2025). "PML protein act as transcriptional regulator, its function is a wide range of important cellular processes, including tumor suppression, transcriptional regulation, apoptosis, senescence, DNA damage response, and viral defense mechanisms." (PMID 40005074, 2025). "SCP1 stabilized PML, which led to enhanced tumor-suppressive effects regarding proliferation, migration, invasion tumor growth, and tumor angiogenesis." (PMID 40723250, 2025). "PML vesicles, 0.1–1.0 μm in diameter, are membraneless nuclear substructures that function as tumor suppressors via regulating cell cycle, senescence, programmed cell death and DNA damage response." (PMID 39006762, 2024). "Beyond APL, PML NBs have emerged as key players in a wide variety of biological functions, including tumor-suppression and SUMO-initiated protein degradation, underscoring their broad importance." (PMID 38611029, 2024). "PML was reported to sustain tumor progression via many mechanisms that include upholding cancer stem cell maintenance, impinging on metabolic pathways and promoting metastasis." (PMID 38730056, 2024). "Pharmacological inhibition of PML with an FDA-approved drug impairs tumor expansion in preclinical ccRCC models." (PMID 38730056, 2024). "We demonstrate that USP22 controls basal stability of tumor-suppressive PML and identify a destabilizing role of PML K394." (PMID 38467608, 2024). "PML is a tumor suppressor that regulates mitochondrial ferroptosis in cancer, most probably through a stress-mediated PML-PGC-1α-dependent mechanism, enhancing ferroptosis sensitivity." (PMID 39739972, 2024). "Its close ties to tumor occurrence, development, and treatment resistance encompass aspects such as DNA repair, transcriptional regulation, expression of proto-oncogenes and tumor suppressor genes, as well as the formation of PML bodies and SGs." (PMID 38383403, 2024). "Mechanistically, PML inhibits tumor cell proliferation, migration, and invasion; it promotes apoptosis and senescence." (PMID 39253293, 2024). "PML knockdown, which was verified by IHC at the experimental endpoint, dramatically reduced tumor expansion." (PMID 38730056, 2024). "Histopathological evaluation revealed that tumors generated with both cell lines were of high grade (mostly nucleolar grade III–IV), with reduced tumor grade upon PML knockdown (control tumors: 7/7 grade IV; PML-depleted tumors: 4/7 grade III, 3/7 grade IV)." (PMID 38730056, 2024).
tumor (continued). "The ubiquitous PML-NBs sequester and release a wide range of substrates in order to regulate several crucial cellular processes (DNA repair, tumour suppression, apoptosis, antiviral responses, etc...)." (PMID 38583183, 2024). "In ruminants, research has revealed that a specific gene called PML plays a crucial role in inhibiting tumor growth, indicating a potentially enhanced cancer prevention system in these animals." (PMID 39748948, 2024). "Promyelocytic leukemia protein (PML) nuclear bodies (NBs) are essential in regulating tumor suppression, antiviral response, inflammation, metabolism, aging, and other important life processes." (PMID 39587079, 2024). "This was investigated in a later study, where PML was positioned downstream the SCP1 phosphatase, a protein with tumor-suppressive functions in ccRCC that promotes PML stabilization." (PMID 38730056, 2024). "In a study investigating the role of the SCP1 phosphatase, which promotes PML degradation, it was suggested that PML exerts tumor-suppressive functions in ccRCC." (PMID 38730056, 2024). "PML was initially described as a protein endowed with tumor-suppressive functions in cancer, but accumulating evidence points to a more complex scenario of tumor suppression or promotion that depends on the tissue context." (PMID 38730056, 2024). "Collectively, these results extend previously published observations by confirming that PML is overexpressed at the mRNA and protein level in ccRCC specimens, and showing that PML upregulation is tumor cell-intrinsic." (PMID 38730056, 2024). "Some studies have also unraveled a tumor-promoting role for PML through control of stemness and metabolic rewiring." (PMID 37382966, 2023). "At P3, parental, primary tumor and lung‐derived KD PML cells exceeded their controls in pairwise comparisons." (PMID 37518985, 2023). "The inactivation of the promyelocytic tumor suppressor PML leads to cancer susceptibility, while PIAS1 activates the SUMOylation process of PML, leading to its degradation." (PMID 37670258, 2023). "The transcriptional functions of PML are of particular interest in cancer, where PML has been described as a tumor suppressor or oncogene depending on tumor contexts." (PMID 37823593, 2023). "Promyelocytic leukemia protein (PML) modulates diverse cell functions that contribute to both tumor suppressor and pro‐oncogenic effects, depending on the cellular context." (PMID 37518985, 2023). "First, we analyzed the expression levels of MELK, PYCR1, and PML according to the TCGA database, and we showed that the three hub genes were upregulated in ccRCC tumor tissues compared with matched normal tissues." (PMID 37340189, 2023). "Janssen and co-workers reported that VP3 directly interacts with PML in tumor cells and confirmed that it accumulates in PML NBs." (PMID 37127643, 2023). "Gross observation and stereomicroscopy of autopsied tumor‐bearing mice showed that all (7/7) the KD PML expressing, MDA‐MB‐231 tumors, had a more intense metastatic load relative to controls in all the organs examined." (PMID 37518985, 2023). "The increased lung metastatic ability of MDA‐MB‐231 KD PML‐derived tumor lines was maintained upon secondary xenografting." (PMID 37518985, 2023). "Some evidence points to tumor stem cell senescence as the driver of PML-dependent cancer cell clearance." (PMID 37382966, 2023). "Given the multifaceted function of PML in this tumor context, we aimed to provide mechanistic insights into PML transcriptional regulation at a whole genome level." (PMID 37823593, 2023). "Upon exposition to chemical tumor initiators, PML-null mice develop significantly more tumors than their wild-type counterparts, particularly in the presence of another activated oncogenic pathway." (PMID 37382966, 2023). "Initially, we tested the tumor xenograft growth ability of PML control along with the MDA‐MB‐231 KD PML lines #0 and #2 that showed a significant reduction of PML expression." (PMID 37518985, 2023).
tumor (continued). "Previous study reported that PML act dual roles as oncogenic drivers and tumor suppressors in various malignant tumor." (PMID 36776317, 2023). "PML is a tumor suppressor response to environmental stimuli and crucial to antiviral defense activities." (PMID 37189176, 2023). "All PML control and KD lines derived from tumor tissue retained differential expression of PML RNA, and protein, similar to their parental cell lines." (PMID 37518985, 2023). "Histology of primary MDA‐MB‐231 KD PML tumor sites showed reduced necrosis relative to control group." (PMID 37518985, 2023). "Vibrant PML research has developed in multiple labs, focused on cell biology, virology, biochemistry, and roles of PML as a key modulator of stress response and tumor suppression." (PMID 37382966, 2023). "The tumor-suppressor PML protein is the primary scaffold of PML NBs and forms an outer shell, together with the SP100 nuclear antigen, surrounding an inner core of dozens of proteins that localize constitutively or transiently in PML NBs." (PMID 37227756, 2023). "The down-regulation of PML protein expression in the tissues of many cancer patients suggests that PML as a tumour suppressor initiates carcinogenesis when down-regulated." (PMID 36104345, 2022). "In contrast, PML has an uncharacteristic pro-tumor function in triple negative breast cancers by promoting fatty acid oxidation." (PMID 35178392, 2022). "PML bodies organize the repression of the E2F target genes required for cell proliferation by organizing repression compartments with the retinoblastoma tumor suppressor." (PMID 35406602, 2022). "For example, PML was shown to repress pro-tumorigenic autophagy as part of its tumor suppressor activities." (PMID 36158205, 2022). "PML plays a role in many important cellular processes, including tumor suppression, apoptosis, transcriptional regulation, DNA damage response, senescence, and viral defense mechanisms." (PMID 35729564, 2022). "A previous study reported that WDR4 promotes the proteasomal degradation of promyelocytic leukemia (PML) tumor suppressor in LC." (PMID 35590385, 2022). "The promyelocytic leukemia protein PML acts as tumor suppressor, regulating apoptosis and cellular senescence." (PMID 35406602, 2022). "In APL RNF4 mediates the SUMO-dependent ubiquitination and subsequent degradation of the oncogenic driver PML-RARα, leading to differentiation of the tumor cells." (PMID 36153321, 2022). "In HCC, Efp suppressed expression of TRIM19, a tumor suppressive protein also known as promyelocytic leukemia protein (PML)." (PMID 35954308, 2022). "We study the PML-mediated effects regarding the tumor growth and invasive properties using 2D and 3D biological models and wide field/confocal microscopy." (PMID 34208139, 2021). "Since the discovery of PML as a tumor suppressor, many important cellular functions have been associated with this protein." (PMID 33546431, 2021). "Our results demonstrate a successful clinical application of the PU-FITC-binding assay in a post-transplant, relapsed AML patient with PML-SYK fusion whose tumor cells demonstrated epichaperome abundance." (PMID 34040147, 2021). "A significant downregulation of PML and NFκB target genes associated with tumor suppressive functions (RASSF6, NLRP12) was observed in HCVtg PML−/− mice." (PMID 33807177, 2021). "Since the clinical RA administration was known to induce blast differentiation and complete remission in APL patients, PML was thereby classified as a tumor suppressor, and oncogenic regulation has since been considered an important function of PML-NBs." (PMID 33546431, 2021).
tumor (continued). "The tumour suppressive function of PML was first suggested by discovery of its disruption in a chromosome rearrangement that is characteristic of acute PML; the resulting fusion protein acts as a dominant-negative to block the activity of normal PML protein." (PMID 34215258, 2021). "We genetically modified the cells to conditionally overexpress the PML isoform IV and we focused on its dual role in tumor growth and invasive capacity." (PMID 34208139, 2021). "Another latency factor, EBNA 1 protein that is responsible for viral DNA replication and EBV persistence, induces protein degradation of promyelocytic leukemia (PML) tumor suppressor, inhibiting the formation of nuclear bodies (PML NBs)." (PMID 33919876, 2021). "PML and the PML nuclear domain have been regarded as a tumor‐suppressive role in several different types of cancer." (PMID 34741430, 2021). "PML deficiency in HCV-transgenic (HCVtg) PML-deficient (PML−/−) mice enhanced susceptibility to tumor induction by diethylnitrosamine (DEN)/phenobarbital (PB) treatment compared to WT, HCVtg, and PML−/− mice groups by enhancing hepatocyte proliferation." (PMID 33807177, 2021). "Overall, our findings indicate that, in GB, PML inhibits tumor growth while it modulates cellular migration and these two PML-driven functions are mediated by distinct cellular mechanisms." (PMID 34208139, 2021). "HEK-293 cells have an inactivation of the RB and PML tumor suppressor pathways due to expression of adenovirus E1A oncoprotein." (PMID 34676390, 2021). "Briefly, OTUD5 potentially inhibits tumor progression by regulating PML transcription by deubiquitinating TRIM25." (PMID 32826889, 2020). "The role of PML in tumor suppression has been extensively investigated, and accumulating evidence indicates that PML also has roles in stem cells." (PMID 33067577, 2020). "The knockdown efficiency of OTUD5 and the levels of TRIM25 and PML in the tumor tissues formed by the OTUD5-depleted cells were determined by RT-PCR." (PMID 32826889, 2020). "Here, the data presented support the notion that the bulk of tumor cells in a TNBC with elevated PML is “addicted” to the expression of the protein." (PMID 31570853, 2020). "Initially viewed as a tumor suppressor, the PML protein lately re-emerged as a multifaceted molecule that controls many different aspects of cellular homeostasis." (PMID 32737302, 2020). "To assess the OTUD5-mediated PML regulation in tumor development under more physio pathologically relevant conditions, we also investigated PML expression and its correlation with OTUD5 levels in NSCLC." (PMID 32826889, 2020). "Of note, PML is required for a fully functional senescence response upon oncogene activation in tumors where it functions as a tumor suppressor." (PMID 31570853, 2020). "Because PML protein was initially described as a tumor suppressor, studies investigating PML have mainly focused on its roles in apoptosis, cell cycle regulation, tumorigenesis and tumor metastasis." (PMID 33324553, 2020). "Among genes directly modulated by miR-337-3p is the promyelocytic leukemia protein (PML), a tumor suppressor regulating several cellular processes including proliferation, apoptosis, or antiviral response." (PMID 32937758, 2020). "The PML tumor suppressor was among the differentially expressed genes showing the greatest variability." (PMID 32826889, 2020).